APC (APC regulator of Wnt signaling pathway)
Diseases named in the same sentence as APC in open-access papers (continued):
Sharing a sentence is not in itself a finding about the gene and the disease.
cancer (1,553 papers, 2000 to 2026). A tumor composed of atypical neoplastic, often pleomorphic cells that invade other tissues. "The first link between Wnt signaling and human disease was established with familial adenomatous polyposis, a cancer caused by mutations in the adenomatous polyposis coli (APC) gene." (PMID 41541657, 2026). "Canonical Wnt/β‐catenin signaling is frequently hyperactivated in cancers, often via mutations in pathway components such as APC or β‐catenin." (PMID 41541657, 2026). "She received genetic testing using a cancer gene panel comprising 46 genes, including the APC gene, which revealed a heterozygote pathogenic variant in the promotor 1B of the APC gene, NM_001127511.3: c.‐191T > C." (PMID 41523585, 2026). "As a key regulator of multiple cell cycle events, APC/C dysfunction is associated with various human diseases, particularly cancer." (PMID 41159544, 2026). "Mutations from individual cancers and the relative frequencies of all expected truncations arising from the known signatures were mapped to their locations within the APC gene." (PMID 41339549, 2026). "This is the first time a population-based prospective cohort study has been used to assess the cancer risks associated with APC I1307K." (PMID 40866199, 2025). "Dysregulation of APC/C: Cdc20 can lead to genomic instability and is implicated in various diseases, including cancer." (PMID 40565031, 2025). "This process is often upregulated in cancer, frequently due to stabilizing mutations in β-catenin or loss-of-function mutations in the tumor suppressor gene APC (adenomatous polyposis coli)." (PMID 40869407, 2025). "The association between CD40 and APC was also evaluated using the TCGA Pan-Cancer Atlas cohort, confirming that APC alterations were significantly more frequent in the non-high CD40 group than in the high CD40 group." (PMID 41182434, 2025). "EMOGI successfully identified diverse genetic alterations in well-established cancer genes, including APC high mutation frequency in colon cancer, TWIST1 promoter hypermethylation, and MYC copy number amplifications across multiple cancer types." (PMID 40565540, 2025). "Among the numerous genetic variations associated with increased risks of certain conditions, the adenomatous polyposis coli (APC) gene, specifically the I1307K mutation, emerges as a genetic variant with notable implications for cancer predisposition." (PMID 40657252, 2025). "To achieve this, we focused on a cancer-specific marker: the C-terminal truncated mutation of the APC protein, which is reported in 60–70% of CRC patients." (PMID 39858085, 2025). "The role and timing of cancer-associated mutations, such as those in APC and CTNNB1, in LS-associated tumorigenesis have been studied recently." (PMID 40753397, 2025). "Genetic testing offers several advantages, including the definitive confirmation of FAP, exclusion of other polyposis syndromes, identification of at-risk relatives, and more accurate cancer risk assessment based on specific APC variants." (PMID 41523393, 2025). "Hyperactive WNT/β-catenin signaling, often driven by APC loss, is a well-established pan-cancer mechanism for fostering an immune-excluded microenvironment by preventing T-cell infiltration, providing a mechanistic basis for the observed low CD40 expression." (PMID 41182434, 2025). "Overall, SBS88 and ID18 accounted for 8.3% of all SBS and ID driver mutations, and 15.5% of all APC driver mutations in colibactin-positive cancers." (PMID 40267983, 2025). "In our previous study, we identified two potential genetic regions termed (frameshift mutation clusters) FSCs in the APC gene, where frameshift mutations generating new peptide sequences common in multiple cancers are accumulated." (PMID 40443649, 2025).
cancer (continued). "Aust et al23 reported that APC expression is reduced in UC-associated cancers and sporadic CRCS compared to normal epithelium." (PMID 40521787, 2025). "The Wnt/β-catenin pathway regulates colonic mucosal epithelial-cell differentiation and is commonly activated in sCRC due to APC gene mutations, leading to the acquisition of stem cell-like characteristics and cancer development." (PMID 40277893, 2025). "In our model, we consider how mutation accumulation in the large bowel leads to biallelic APC-mutated cells, which, in turn, can progress to cancer." (PMID 41091816, 2025). "Second, in cancer-associated APC mutations, the incomplete middle domain of the shortened APC leads to unregulated activity of the intact N-terminus, resulting in uncontrolled cell migration and protrusion." (PMID 40227591, 2025). "We detected the highest mutation frequency (73%) in the APC gene among the five cancer clusters, but the APC wild-type was significantly enriched in W3 cluster (P < 0.001)." (PMID 40357363, 2025). "FAP is associated with germline mutations in APC promoting cancer initiation and chromosomal instability." (PMID 40753397, 2025). "Patients with an APC germline mutation around codon 1309 have an exceptionally severe phenotype, with high polyp burden, early development of cancer and a high risk of progressive disease in the retained rectum if an IRA is performed." (PMID 40911204, 2025). "We established FAP-human embryonic stem cell lines (FAP1,2,3) with distinct APC mutations and differentiated them into colon organoids to study cancer development." (PMID 40695959, 2025). "The frequency of APC mutations in carcinomas, which has been investigated in a large number of studies in TCGA, is 51% in hypermutated tumors and 81% in non-hypermutated tumors." (PMID 41488735, 2025). "This pathway is believed to differ from the traditional AD–carcinoma sequence, in which ADs progress to invasive colorectal carcinomas through a series of genetic changes, including mutations in APC and KRAS." (PMID 40693022, 2025). "The frequency of APC mutation in LG adenomas was 72%, while that in HG adenomas and carcinomas was 72%." (PMID 41488735, 2025). "Regardless of the presence or absence of the endogenous APC, previous works showed that APC-m4 exerts a dominant-negative effect, similar to the cancer-linked C-terminal truncations of APC." (PMID 38680662, 2024). "The best-known and most-studied pathway to CRC is the canonical pathway, in which cancer originates from conventional adenomatous polyps bearing APC (adenomatous polyposis coli) mutation." (PMID 38921956, 2024). "The sensitivity of cancers with alternatives to APC mutations in the WNT/APC/β-catenin pathway remains to be determined as these inhibitors progress to clinical trials." (PMID 39452477, 2024). "Centrinone-induced cancer organoid growth defect/death positively correlated with a loss of function mutation in the APC gene, suggesting a causal role of the hyperactive WNT pathway." (PMID 38324534, 2024).
cancer (continued). "We extend those findings to human cancers and show that APC loss-of-function mutations as well as reduced expression are strongly correlated with 3′ UTR lengthening for many RNA targets." (PMID 39375704, 2024). "In contrast, KRAS mutated cancers are distributed throughout the colon tending to co-occur with APC mutations, with a higher tendency in the distal colon cancers." (PMID 38360902, 2024). "The gene APC also demonstrated three hotspot associations in closely related cancers, colon and rectal, all of which were associated with a lower risk." (PMID 38473427, 2024). "In this series, we reported four cases of APC increased risk allele; despite the fact that a missense variant in codon 1307 variant carries low penetrance, it increases risks for multiple cancers especially in Ashkenazi Jewish ancestry." (PMID 38730621, 2024). "A total of 75 index cases with CPs and a personal/family history of cancer were analyzed to identify genetic alterations in major hereditary polyposis-associated genes (APC, BMPR1A, MUTYH, PTEN, SMAD4, STK11)." (PMID 39518056, 2024). "We also identified new domains of Axin and APC that drive phase separation, providing more detailed insights into the molecular mechanisms of malignant tumors associated with Wnt pathway activation." (PMID 38279052, 2024). "Cancer-associated truncated mutants of APC destabilized this interaction, leading to derailed mitochondrial distribution." (PMID 38607086, 2024). "Lastly, because the study is cross-sectional, we can’t establish a direct cause-and-effect relationship between APC methylation and cancer progression." (PMID 39569232, 2024). "CIN has been well-described in several cancers, perhaps most famously in colorectal cancer, where mutations in the APC gene result in dysregulation of WNT signaling as well as interference with microtubule function during mitosis, leading to a CIN phenotype." (PMID 39012509, 2024). "For instance, the loss of APC disrupts the Wnt signaling pathway in cancer stem cells, hyperactivating Ras and thereby fueling the cancer’s propagation and invasion." (PMID 38329598, 2024). "Mutations in the APC gene result in aberrant β-Catenin activity, driving the development of cancer and other human diseases." (PMID 39519092, 2024). "Next-generation sequencing-based genetic diagnostics using a panel of 36 genes linked to hereditary cancer predisposition revealed a maternally inherited APC pathogenic variant c.1660C>T (p.Arg554*)." (PMID 39493133, 2024). "We have shown that metabolic reprogramming in CRC is not only related to the Wnt/β-catenin and APC mutation status of cancer cells but is also closely associated with TME eustress." (PMID 39200280, 2024). "Four (8%) were identified with variants in cancer predisposition genes, including two with APC (mild increased risk), and one each with BARD1 and MUTYH; the latter of which was previously identified in the family." (PMID 38256266, 2024). "Distal colon tends to have CIMP-Low, microsatellite stable (MSS), APC-mutant cancers, with an increased likelihood of KRAS mutations." (PMID 38360902, 2024). "For the two patients with cancerous progression, the first patient was diagnosed as TVA mixing with carcinoma at the initial time and contained somatic mutations including APC, KRAS, and ARID1A." (PMID 39554798, 2024). "Beyond β-catenin mutations, recent reports describe how genetic mapping can lead to therapeutics by restabilizing the destruction complexes such as in cancers with APC-truncating mutations." (PMID 37682999, 2023).
cancer (continued). "Traditionally, gene fusions in cancer are associated with activation, but fusions involving genes such as APC and NF2 have been shown to result in loss of protein function in the same way that a nonsense or frameshift DNA sequence variant would." (PMID 37646774, 2023). "The clinical implication of harboring the p.I1307K APC variant and the associated cancer risk is still unsettled." (PMID 37107695, 2023). "Overall, the results support that the mechanisms of IL13Rα2-triggered cancer progression are relatively homogenous, with minor differences likely caused by the different genetic background (i.e. APC mutations in CRC)." (PMID 37963919, 2023). "Colon cancer is one of the most common cancers worldwide, and molecular studies have demonstrated the involvement of accumulated mutations in multiple genes, including APC (adenomatous polyposis coli)." (PMID 37117033, 2023). "The β-catenin-dependent Wnt transcriptional activation complex, also known as the Wnt enhanceosome, is probably the most promising drug target for therapeutic intervention in cancers driven by inactivating APC or activating β-catenin mutations." (PMID 37349336, 2023). "For other cancer predisposition genes, including the APC gene, different phenotypes have been described for mutations in different parts of the gene." (PMID 37626374, 2023). "Together, these studies suggest that both BCL9/9l and Pygo1/2 are attractive therapeutic targets in cancers that harbour mutations in both APC and CTNNB1." (PMID 37048063, 2023). "The Wnt enhanceosome is responsible for transactivation of Wnt-responsive genes and a promising therapeutic target for treatment of numerous cancers with Adenomatous Polyposis Coli (APC) or β-catenin mutations." (PMID 37349336, 2023). "The observed negative trend between APC and MDR1 makes this a better targeted therapy option in APC-deficient cancer." (PMID 37108784, 2023). "No preclinical or human studies have shown the association between somatic mutation of APC in cancer cells and their sensitivity to nCRT." (PMID 36621808, 2023). "Altogether, these data support the notion that multiple cancers are initiated by an APC mutation event." (PMID 37468468, 2023). "Genetic consultation and regular follow-ups are necessary for the individualized treatment of cancer-afflicted families with APC expression deficiency." (PMID 37577746, 2023). "It is widely accepted that the Wnt enhanceosome, the nuclear endpoint of the Wnt signaling cascade down-stream of the β-catenin destruction complex, is the most promising target for treatment of cancers with APC or β-catenin mutations." (PMID 37349336, 2023). "The pathological effect of this Wnt pathway activation has been intensively studied in colorectal carcinoma, where APC is typically mutated, and, with that, elevated β-catenin levels lead to cancer development." (PMID 36765639, 2023). "Several Formins (including DAAM1 and DAAM2) are key components of canonical WNT signaling in cancer development, thus they are involved in APC mutation and colon polyp formation." (PMID 37249599, 2023). "APC gene variants have therapeutic implications as well by imparting chemotherapy resistance highlighting the importance of detecting APC variants in cancer patients." (PMID 37277882, 2023). "The inflammation-dysplasia-carcinoma pathway APC dysregulation and KRAS mutations are less frequent than in CRC." (PMID 38187473, 2023). "Regarding the APC pathogenic variant, 21.28% of the patients had the p.Glu1309Aspfs*4 mutation (which is associated with higher risk of cancer)." (PMID 35053462, 2022). "After reviewing all the genes of remaining variants, we excluded APC, which were mainly associated with cancers." (PMID 36118902, 2022).
cancer (continued). "APC was first identified through its association with familial adenomatous polyposis coli (FAP), a syndrome where inherited mutations that delete APC cause colorectal and intestinal adenomatous polyps, increasing the risk of developing cancer." (PMID 35204808, 2022). "We assessed the rate of the APC I1307K variant in patients with different types of cancer and at least 20 cases of the same cancer type." (PMID 36497357, 2022). "Sanger sequencing analysis confirmed the segregation of the detected pathogenic APC variant with the cancer phenotype in this family." (PMID 35495172, 2022). "The risk of dysplasia and cancer is due to a combination of genetic predisposition (germline APC mutation), intestinal epithelial changes due to faecal stasis and the presence of residual rectal mucosa." (PMID 35158797, 2022). "And the functional loss of APC caused by APC mutation facilitates cancer cell survival by inducing HIF-1α expresses." (PMID 35928881, 2022). "APC, the most common cancer gene mutated in CRCs, was mutated in two crypts, one (APC T1556fs) from the duodenum and the other (APC Q8X) from the caecum." (PMID 35581206, 2022). "APC mutation leads to the accumulation of β-catenin protein in the cytoplasm and can promote the proliferation, migration, invasion, and metastasis of cancer cells." (PMID 37125020, 2022). "When APC was mutated in the TMB-H cancers, a more diverse composition of variant types was observed: three missense, three nonsense, one frameshift indels and one splice site variant." (PMID 35740599, 2022). "Despite these limitations, the population in our study is one of the most extensively tested, so far, for the presence of the APC I1307K variant, in which 586/7624 AJ cancer patients and 318/141,673 NAWs with cancer carry the variant." (PMID 36497357, 2022). "We also identified medically actionable variants in eight other cancer-related SFs genes, including APC, MAX, MSH6, MLH1, PALB2, PMS2, SDHB, and TSC2." (PMID 36143288, 2022). "The results demonstrate a significantly higher APC I1307K variant prevalence among AJ than NAW in both cancer patients and healthy individuals (p < 0.001 for both groups)." (PMID 36497357, 2022). "Through a comprehensive analysis of cancer genomes based on deep sequencing, it became evident that mutations in APC, CTNNB1, and Axin are frequently detected in many types of human cancers, such as colorectal and liver cancers, with β-catenin accumulation." (PMID 35053606, 2022). "Both XL177A and P5091 exhibited a more substantialgrowth inhibition effect on the APC-mutated SW480colorectal carcinoma cell line than normal colonic epithelial celllines." (PMID 36589880, 2022). "Loss of APC acts as a screening marker for malignant potential, but the diagnosis of carcinoma still must be proved by WHO criteria, that are based on manifestations of invasive growth and metastatic spread." (PMID 35805976, 2022).